TF (transferrin)
Diseases named in the same sentence as TF in open-access papers (continued):
Sharing a sentence is not in itself a finding about the gene and the disease.
melanoma (continued). "Transferrin is responsible to restrain the intracellular iron pool, whose knockout promoted iron-dependent lipid peroxidation and ferroptosis, which weakened tumorigenic capacity of circulating melanoma cells in the bloodstream." (PMID 36211509, 2022). "Whereas fewer studies have explored the effect of TF-miR-10a-5p on the progression of melanoma." (PMID 34424910, 2021). "Collectively, our studies helped us understand the TF-miR-10a-5p mediated melanoma pathogenesis and may discover novel therapeutic targets for melanoma." (PMID 34424910, 2021). "Additionally, SREBF2 can induce transferrin and inhibit ferroptosis in circulating melanoma cells." (PMID 40335466, 2025). "We established 2 preclinical models of LM in melanoma (intrasplenic injection of B16F10 cells) and lymphoma (subcutaneous injection of EL4 cells) to further investigate the role of transferrin in LM." (PMID 39810853, 2025). "We conclude that transferrin-conjugated nanostructured lipid carriers (NLC-Tfs) are a promising delivery system for Artemisone (ATM), a repurposed antimalaria drug, to melanoma cells." (PMID 39201805, 2024). "Cyclodextrin-based cationic polymer (CALAA-01) in clinical trials has been modified with transferrin and PEG to target the melanoma and prevent the aggregation in the circulation system." (PMID 35631507, 2022). "Skin-Melanoma (401 burdened sites), Myeloid-MPN (296 burdened sites), and Lymph-BNHL (274 sites), were the cancer types with the greatest number of non-coding promoter/TF regions identified." (PMID 33092526, 2020). "Synergy predictions for the prostate carcinoma cell line DU145 were consistently of moderate accuracy (AUC values ∼0.6–0.7), while predictions for the melanoma cell line (UACC62) was consistently the poorest, with an AUC value lower than 0.5 for the TF activity training data set." (PMID 33195403, 2020). "The thrombin generation by MV3 melanoma cells is in principle identical to that of MDA-MB-231 cells, a slightly longer lag time before thrombin activity can be detected and corroborates the lower TF expression, shown before." (PMID 30356007, 2018). "Interestingly, binding sites for MYC TF were also identified in our analysis of CD47 proximal promoter region, however, MYC binding was undetectable in human malignant melanoma within CD47 DNA promoter region between -120bp to +54 relative to TSS required for its activation." (PMID 39742254, 2024). "Here we report that a defined serum free cell culture medium condition containing insulin, transferrin and selenium (ITS) supports controlled study of transcriptional regulation of de novo fatty acid (DNFA) production and de novo cholesterol synthesis (DNCS) in melanoma cell lines." (PMID 30970006, 2019). "Interestingly, infiltration of tumors by CD8+ T cells negatively correlated with levels of TF-antigen residues (studied by ACA fixation) on tumor cells, while positively correlated with levels of β-Gal residues (seen by RPL-Gal4 fixation) on tumor cell lines from melanoma patients." (PMID 36891308, 2023).
liver disease (38 papers, 2009 to 2025). "Higher polygenic score for serum iron and for TF saturation increased risk of liver disease, especially liver fibrosis or cirrhosis and liver cancer." (PMID 35567766, 2022). "We also excluded other major causes of liver disease, such as non-alcoholic fatty liver disease as per ultrasound, excessive alcohol consumption, viral serologies, transferrin saturation, and AST levels." (PMID 33216778, 2020). "Our screening study did not identify V‐ATPase assembly factor defects in a cohort of severe liver disease, but we show that end‐stage liver disease is associated with hyperfucosylation of transferrin." (PMID 32557671, 2020). "An altered iron homeostasis mostly with hyperferritinemia, elevated transferrin saturation and/or an elevated serum iron is reported in multiple liver diseases beyond hemochromatosis and is mostly associated with worse disease course." (PMID 28594937, 2017). "Despite this marker’s high specificity for alcohol related pathology, genetic polymorphism of transferrin, congenital disorders of glycosylation and other severe liver disease may increase S -CDT levels." (PMID 40310581, 2025). "Inborn errors due to rare genetic D-variants of transferrin in glycoprotein metabolism and liver diseases, such as cirrhosis, primary biliary cirrhosis, chronic active hepatic and chronic viral hepatitis, may cause false-positive results." (PMID 25995731, 2015). "Also, because transferrin is a β-globulin produced by hepatocytes, a liver disease that causes hypoproteinemia may cause hypotransferrinemia." (PMID 35812844, 2022). "Normal transferrin saturation helps distinguish HHCS from secondary causes (inflammation, liver disease, infection, autoimmune, metabolic disorders, malignancy)." (PMID 41300832, 2025). "Epidemiological studies reporting elevated serum ferritin and transferrin saturation in populations exposed to industrial chemicals support the clinical relevance of iron dysregulation in environmental liver disease." (PMID 41304484, 2025). "The correlation between hepatic HNF4A and transferrin mRNA levels was also seen in advanced liver disease." (PMID 33593348, 2021). "Here, we studied the mechanisms regulating transferrin production in individuals with advanced liver disease and AH and show that serum transferrin levels reflect the hepatic activity of HNF4α." (PMID 33593348, 2021). "Changes in the TIEF test profile in liver disease represent alterations occurring during biosynthesis of transferrin by the endoplasmic reticulum (ER) and golgi apparatus." (PMID 34440401, 2021). "In patients with advanced liver disease, serum transferrin levels correlated with hepatic transferrin expression (r = 0.51, p = 0.01)." (PMID 33593348, 2021). "Altered iron homeostasis with elevated serum ferritin, transferrin saturation and serum iron is found in multiple liver diseases beyond haemochromatosis." (PMID 29323192, 2018). "A total of 108 individuals with hepatic disease, transferrin saturation (TS) > 45%, and serum ferritin (SF) > 350 ng/mL were tested for HFE mutations." (PMID 25654085, 2015). "Limited serum transferrin-iron saturation measures or HH diagnosis codes among p.Cys282Tyr homozygotes, even those with liver disease, suggests potential undertesting and underdiagnosis of type 1 HH in clinical practice and a need for improved awareness, education, and testing around HH." (PMID 40034140, 2025). "The values of desialylated (carbohydrate-deficient) transferrin (CDT) were highest in the group of heavy drinkers without liver disease." (PMID 37685930, 2023). "Moreover, ferritin is an acute phase protein that can be increased in the process of inflammation, whereas transferrin is downregulated in the process of inflammation and reduced in advanced liver disease, which is in accordance with our results." (PMID 35034629, 2022).
liver disease (continued). "At the same time, we find differences in the transferrin isoform profile in other liver diseases; in rheumatic diseases, including rheumatoid arthritis, systemic lupus erythematosus, systemic sclerosis and juvenile idiopathic arthritis; and in pancreatic cancers." (PMID 35329964, 2022). "Transferrin is synthesized by the liver, so the low transferrin concentration may be attributed to liver disease, consequently decreasing the iron-binding capacity." (PMID 35246767, 2022). "To delineate the factors underlying the predictive usefulness of transferrin in severe liver disease, we compared the hepatic expression of transferrin and transferrin serum levels in 23 patients with advanced liver disease and available matched mRNA-serum sample pairs (cohort i)." (PMID 33593348, 2021). "While we focused on AH and advanced liver disease, the decreased transferrin levels seen in individuals with acute liver failure and in critically ill patients suggest that similar mechanisms may apply to multiple different stress situations." (PMID 33593348, 2021). "In combination with our findings, it is tempting to propose that transferrin synthesis might increase during the early stage of liver disease, and thereafter it decreases as fibrosis advances as a result of reduced capacity of transferrin synthesis." (PMID 28439208, 2016). "Pathway-specific therapeutic intervention using rapidly evolving RNA/protein-targeting technologies may be possible in near future, but research efforts utilizing humanized liver disease models should before scrutinize the pros and cons of targeting hepatic TF-co-regulator networks." (PMID 31293521, 2019). "Also, with liver disease, an iron overload state can occur which provides a more favorable environment for Vibrio growth since the organism is impaired in its ability to extract iron from transferrin." (PMID 24455339, 2013). "The candidate biomarkers identified in this study—particularly hepcidin, ferroportin, ferritin, transferrin saturation, and GLDH—offer potential tools for early detection and monitoring of environmental liver disease." (PMID 41304484, 2025). "In our retrospective analysis of a cohort of 1042 liver disease patients, we found a significant percentage of patients with altered CDG screening results by serum transferrin isoelectric‐focusing." (PMID 32557671, 2020). "The biochemical data related to nutritional status, including total cholesterol, serum albumin, transferrin, prealbumin, and CRP, are influenced by medical conditions, including malignancy, liver disease, infection, stress, and critical illness." (PMID 32053672, 2020). "Of the 71 participants who were p.Cys282Tyr homozygotes with indication of liver disease, 32 (45.1%) did not have a serum transferrin-iron saturation measure, and 37 (52.1%) did not have diagnosis codes for HH." (PMID 40034140, 2025). "It is important to note that albumin and transferrin levels do not always reflect actual protein status, since they are affected by other conditions, including inflammation, liver disease, and nephrotic syndrome, which were not investigated in this study." (PMID 29324643, 2018). "Reduced transferrin and increased alpha-2-macroglobulin in HBV carriers might suggest active liver disease." (PMID 19860894, 2009). "Diagnosis relies on the detection of persistently elevated serum ferritin with otherwise normal iron parameters (serum iron, transferrin saturation, and total iron-binding capacity), absence of inflammation or liver disease, and the presence of early-onset bilateral cataracts." (PMID 41300832, 2025). "Interestingly, the present data also show significant correlations between anti-tTG antibodies and desialylated transferrin even in alcohol consumers without liver disease." (PMID 37685930, 2023).
hyperferritinemia (37 papers, 2010 to 2026). "Another rare genetic cause related to hyperferritinemia with a normal transferrin saturation is Gaucher disease." (PMID 34067164, 2021). "Of the 176 individuals reported with SLC40A1 mutations, 80 were classified as classical phenotype with hyperferritinemia and normal transferrin saturation." (PMID 20691492, 2010). "Dysmetabolic hyperferritinemia (DHF) was first described when HF with normal transferrin saturation was linked to metabolic disorders and has further been referred to as insulin resistance-associated hepatic iron overload with additional positive histological iron staining." (PMID 38255312, 2024). "Instead, when the percentage of transferrin saturation is normal, hyperferritinemia can be associated with hepatic cytolysis, hemolysis, cancer, hyperthyroidism or chronic alcohol abuse, whereas a low transferrin value suggests the presence of an inflammatory syndrome." (PMID 35741435, 2022). "Although non-HH factors like alcoholism, NAFLD and nonalcoholic steatohepatitis (NASH) are associated with hyperferritinemia from chronic inflammation, the patient’s elevated transferrin saturation [(serum iron/total iron binding capacity) × 100] can only be explained by her HH status." (PMID 33596964, 2021). "We report the case of a 58-year-old male patient with longstanding unexplained hyperferritinemia, normal transferrin saturation, and a striking multigenerational family history of early-onset cataracts." (PMID 41769540, 2026). "It is important to highlight that a previous diagnosis of hereditary hemachromatosis or transferrin saturation (> 50%) are exclusion criteria for metabolic hyperferritinemia." (PMID 41283478, 2025). "While European guidelines recommend screening using ferritin and transferrin-saturation (TSAT), inconsistent diagnostic criteria, especially regarding functional deficiency (ferritin 100–299 μg/L + TSAT < 20%) and hyperferritinemia, limit prognostic accuracy." (PMID 41517493, 2025). "Ophthalmologists should consider ferritin testing in patients with unexplained cataracts and a suggestive family history, while hematologists should evaluate for ocular involvement in cases of persistent hyperferritinemia with normal transferrin saturation." (PMID 41300832, 2025). "Key differentiators between DIOS versus hereditary hemochromatosis include iron deposition in mesenchymal cells (Kupffer cells or other macrophages), presence of metabolic syndrome, and hyperferritinemia with normal transferrin saturation." (PMID 39057678, 2024). "There is evidence indicating hyperferritinemia with normal transferrin saturation is an indicator of glucose–lipid metabolism disorders." (PMID 36824177, 2023). "The canonical form, presenting as hepatic and spleen iron overload, is characterized by hyperferritinemia, normal to low transferrin saturation, and Kupffer cell iron storage." (PMID 36295822, 2022). "DIOS is clinically defined on the basis of the following findings: the presence of MetS components, hyperferritinemia with normal transferrin saturation, and mild hepatic iron excess typically with sinusoidal accumulation." (PMID 36496443, 2022). "It is clinically diagnosed with hyperferritinemia, normal or moderately increased transferrin saturation, and the presence of MetS components." (PMID 36496443, 2022). "Aceruloplasminemia most often presents with a low transferrin saturation in the setting of an atypical microcytic anemia with paradoxical hyperferritinemia." (PMID 34067164, 2021). "In the classical form, the loss-of-function mutants of ferroportin prevent iron export from cells, resulting in hyperferritinemia, a normal to low transferrin saturation, and iron accumulation predominantly in reticuloendothelial cells." (PMID 33673803, 2021). "Hyperferritinemia with normal transferrin saturation is a common finding in naïve patients with GD120, with prevalence ranging between 63 and 81%21,22." (PMID 33510429, 2021).
hyperferritinemia (continued). "It has been reported that hereditary hyperferritinemia cataract syndrome (HHCS) should be considered in the differential diagnosis of childhood hyperferritinemia, especially in the presence of normal transferrin saturation." (PMID 32832142, 2020). "Multiple logistic regression analysis of the odds of hyperferritinemia, high transferrin saturation, and high iron by quartile of lung function." (PMID 32240239, 2020). "The baseline hyperferritinemia was accompanied by a high serum iron, elevated transferrin saturations and mild hepatic iron depositions in the majority of patients." (PMID 28594937, 2017). "On the other hand, hyperferritinemia with normal or mildly elevated transferrin saturation is observed in approximately one-third of patients with metabolic syndrome (MetS) or nonalcoholic fatty liver disease (NAFLD)." (PMID 25215659, 2014). "Blood tests showed marked hyperferritinemia and hypoferremia with normal transferrin but decreased transferrin saturation." (PMID 20801540, 2010). "In addition to high serum iron (>300 μg/dl) and visualized iron deposition in liver Kupffer cells (hemochromatosis), dolphins with iron overload have hyperferritinemia and moderately elevated transferrin saturation that increase with age." (PMID 39057678, 2024). "A basic approach to hyperferritinemia is evaluation of transferrin saturation." (PMID 36768886, 2023). "In this hypothesis test, genotypes were testedonly for positive family history for hyperferritinemia, transferrin saturation,rate of bleeds per month." (PMID 37216649, 2023). "Additionally, increased transferrin saturation, hepatocellular iron overload, hyperferritinemia, and macrophage iron loading are considered to be typical features of the non-classical phenotype." (PMID 36295822, 2022). "In the nonclassical form, ferroportin mutations are responsible for a gain of function with full iron export capability but insensitivity to downregulation by hepcidin, leading to increased transferrin saturation and iron accumulation in hepatocytes in addition to hyperferritinemia." (PMID 33673803, 2021). "The non-classical phenotype with hyperferritinemia and elevated transferrin saturation was present in 53 patients." (PMID 20691492, 2010). "On the other hand, when transferrin saturation was evaluated in the 66 volunteers by means of TIBC, only 4.5% of the population presented high levels of iron, and not one of the volunteers diagnosed with hyperferritinemia presented abnormal values of TIBC." (PMID 26451235, 2015).